CX3CR1 (C-X3-C motif chemokine receptor 1)
Diseases named in the same sentence as CX3CR1 in open-access papers (continued):
Sharing a sentence is not in itself a finding about the gene and the disease.
peripheral nerve injury (6 papers, 2016 to 2023). Injury to a peripheral nerve. "Since the increase in the number of sNAMs was only partially reduced in CX3CR1 deficient mice, it is plausible that other signaling pathways are involved in the activation/proliferation of sNAMs in the DRGs after peripheral nerve injury." (PMID 37254842, 2023). "Studies have shown that chronic pain in rodents can be delayed or alleviated by intrathecal administration of neutralizing antibodies against FKN or CX3CR1 in different types of animal models of peripheral nerve injury." (PMID 37273906, 2023). "In particular, there during a critical time window of at POD0–POD5, when CX3CR1+ cells promote the transition from acute to chronic pain after peripheral nerve injury." (PMID 27349690, 2016). "In addition, we found that CX3CR1 signaling is involved in the sNAMs proliferation and neuropathic pain development after peripheral nerve injury." (PMID 37254842, 2023). "Altogether, these results indicate that the CX3CR1+ resident macrophage population is expanding, accounting for the increase in the number of macrophages in the sensory ganglia and neuropathic pain (e.g. mechanical allodynia) development observed after peripheral nerve injury." (PMID 37254842, 2023). "Therefore, the two populations of CX3CR1+ cells may synergistically promote the transition from acute pain to chronic pain after peripheral nerve injury." (PMID 27349690, 2016). "We took advantage of the transgenic reporter mice Cx3cr1GFP/+/Ccr2RFP/+ to trace tissue-resident macrophages (CX3CR1+) and monocytes recruited from the blood to inflamed tissue (CCR2+) after peripheral nerve injury." (PMID 37254842, 2023). "Consistent with that possibility, the chemokines CCL2, CCL3, and CX3CL1 are all highly expressed after peripheral nerve injury with the corresponding chemokine receptors, CCR2, CCR5, and CX3CR1 expressed by NK cells." (PMID 30712871, 2019). "The CX3CR1/p38-MAPK pathway has been suggested to play roles in the microglial activation and the persistence of neuropathic pain in peripheral nerve injury models." (PMID 30622457, 2018). "In summary, the present study elucidates that the increase of sNAMs in the DRG triggered by peripheral nerve injury is a result of resident CX3CR1+ macrophage proliferation and does not depend on blood-derived monocyte infiltration." (PMID 37254842, 2023). "Altogether, these results indicated that sNAMs are the main source of CX3CR1 signaling-dependent pro-inflammatory cytokines (e.g. IL-b and TNF) in the sensory ganglia after peripheral nerve injury, whereas IL-6 seems to be induced mainly in non-immune cells." (PMID 37254842, 2023).
systemic candidiasis (6 papers, 2016 to 2025). "In humans, the dysfunctional CX3CR1 allele CX3CR1-M280 was associated with increased risk of systemic candidiasis." (PMID 40508161, 2025). "CX3CR1 mediated phagocytes by kidney resident macrophages initiate within the first hours during the innate host defense against Candidiasis, confirmed by CX3CR1-M280 associated susceptibility to systemic candidiasis in humans." (PMID 34093584, 2021). "CX3CR1-deficient mice are susceptible to Candida infection, possibly due to reduced numbers of kidney-resident and -infiltrated macrophages." (PMID 29312319, 2017). "Reduced number of renal infiltrating macrophages in infected CX3CR1-deficient mice significantly exacerbates systemic candidiasis." (PMID 28217127, 2017). "Previous research has shown that CX3CR1 dysfunction increases susceptibility of mice and humans to systemic candidiasis." (PMID 27891323, 2016). "The CX3C-chemokine receptor 1 (CX3CR1) on the macrophage surface is essential in the resistance process to candidiasis." (PMID 34234752, 2021). "The CX3CL1/CX3CR1 axis has also been shown not to be essential for mucosal infection, indicating that different factors are involved in the control of mucosal candidiasis and systemic candidiasis." (PMID 40508161, 2025).
co-infection (5 papers, 2017 to 2025). "Increased CX3CR1 expression on CD4+ and CD8+ T cells in PLWH has been associated with CMV co-infection, with an enrichment of CMV-specific populations, some of which target the vascular endothelium." (PMID 40920867, 2025). "Elevated levels of CX3CR1 are also observed in HIV‐Mtb co‐infection, another disease where Mtb reactivation is of great burden." (PMID 34765193, 2021). "The endothelial-expressed lymph node homing receptor CX3CR1 is an important cell population in individuals with HIV/CMV co-infection, which could promote tumor and viral clearance and may provide a source of cells that respond to immunotherapies in the future." (PMID 38674036, 2024). "During HIV-1/Treponema pallidum co-infection, compared with the healthy control group, the density of CX3CR1 was increased in all three monocyte subsets; the increase in CX3CR1 expression on monocytes indicates the presence of systemic inflammation during HIV-1/Treponema pallidum co-infection." (PMID 38674036, 2024). "The expression of CX3CR1 on CD4 and CD8 T cells is similar after induction by DENV, ZIKV, and HBV infections, as well as DENV/ZIKV co-infections, which facilitates the regulation of viral processes by precisely controlling inflammatory cells that target the affected tissue." (PMID 38674036, 2024).
dengue (5 papers, 2018 to 2026). "Asymptomatic dengue is enriched for lower tetramer binding cells with moderate cytotoxic programs, whereas dengue hemorrhagic fever is associated with high tetramer binding CX3CR1 + CD8 + T cells exhibiting enhanced expression of genes related to T cell receptor signaling and cytotoxicity." (PMID 42236711, 2026). "Previous studies also indicated that CD4+ EMRA cells could demonstrate cytotoxic features and express the chemokine receptor CX3CR1 in the setting of Dengue virus infection, which are associated with cytotoxic lymphocytes with cytoplasmic granules containing perforin and granzymes." (PMID 35287794, 2022). "Recent studies have uncovered the significance of highly polarized CX3CR1+ cytotoxic CD4+ T cells in dengue." (PMID 40431664, 2025). "Recent studies have identified highly polarized CX3CR1+ cytotoxic CD4+ T cells in dengue patients, which exhibit potent antiviral activity and could serve as targets for novel vaccine strategies." (PMID 40431664, 2025). "Similarly, augmented expression of CX3CR1 also tends to favor CD4+ CTL transmigration into inflamed tissue, as exemplified in Dengue, where virus-specific CX3CR1 CD4+CTLs mediate protective cytotoxicity." (PMID 34721397, 2021).
encephalitis (5 papers, 2019 to 2025). An acute inflammatory process affecting the brain parenchyma. "Taken together, our results highlight MAVS-dependent induction of the antigen presentation machinery of long-lived CX3CR1+ CNS cells such microglia as a novel critical mechanism of microglia-CD8+ T cell interaction during viral encephalitis." (PMID 40619428, 2025). "In contrast, CX3CR1+/+ and CX3CR1−/− mice showed similar kinetics for encephalitis score after intranasal and intraperitoneal inoculation, although CX3CR1−/− mice showed rapid clinical signs of encephalitis compared with CX3CR1+/+ mice." (PMID 31316515, 2019). "Furthermore, CX3CR1−/− mice scored higher for clinical signs of encephalitis than CX3CR1+/+ mice after peripheral JEV inoculation." (PMID 31316515, 2019). "CX3CR1−/− recipients of CX3CR1+CD11c+ DCs also showed clinical scores for encephalitis comparable to CX3CR1+/+ wild-type mice whereas CX3CR1−/− mice not injected with CX3CR1+CD11c+ DCs showed a higher encephalitis score." (PMID 31316515, 2019).
fibrosis (5 papers, 2012 to 2022). the formation of excess fibrous connective tissue in an organ or tissue in a reparative or reactive process. "Bone marrow transplanted chimeric animals revealed that CX3CR1 restricts hepatic fibrosis progression and monocyte accumulation through mechanisms exerted by infiltrating immune cells." (PMID 23259611, 2012). "In addition, cardiac fibrosis, apoptosis and CVB3 presence were more pronounced and titin was dysregulated in CX3CR1-/- CVB3 mice compared to WT CVB3 mice." (PMID 28800592, 2017). "In this report, we found that mTOR inhibitor rapamycin or mTOR deletion in CX3Cr1+ mononuclear phagocytes inhibits expression of interleukin (IL) −23, accompanied by reduced intestinal production of IL-22 and ameliorated fibrosis in the TNBS-induced fibrosis mouse model." (PMID 30765845, 2019).
Glucose intolerance (5 papers, 2015 to 2022). Glucose intolerance (GI) can be defined as dysglycemia that comprises both prediabetes and diabetes. "CX3CR1-deficient mice exhibit glucose intolerance mainly due to beta cell dysfunction, while fractalkine treatment improves glucose tolerance and increases insulin secretion in wild-type mice." (PMID 35871167, 2022). "Based on glucose tolerance testing and hyperinsulinemic clamps, our results showed a moderate and reproducible protective effect of Cx3cr1 deficiency on HFD-induced glucose intolerance, and enhanced hepatic insulin sensitivity." (PMID 26393344, 2015). "Lee and colleagues also showed that CX3CR1−/− mice developed glucose intolerance with diminished insulin secretion on both regular chow and HFD." (PMID 34948325, 2021). "While both groups demonstrated glucose intolerance with HFD, the effect was lower in Cx3cr1-/- mice suggesting reduction of HFD-induced glucose intolerance." (PMID 26393344, 2015). "Finally, male mice develop glucose intolerance during HFD feeding irrespective of genotype, while only females deficient in CX3CR1 become substantially glucose intolerant." (PMID 28223698, 2017).
HCMV infection (5 papers, 2017 to 2024). "One of the upregulated genes in high-DNAemic samples, CX3CR1, is upregulated in HCMV specific T-cells following HCMV infection." (PMID 33489936, 2020). "As selective action towards US28 is a perquisite to avoid side effects from inadvertent killing of CX3CR1-expressing cells, the prototype F49A-FTP still presents the best candidate therapeutic to treat HCMV infections." (PMID 28251165, 2017).
infarction (5 papers, 2013 to 2026). A localised pathological necrosis of tissue resulting from obstruction of the blood supply usually by a thrombus, an embolus, or vascular torsion. "The analysis of CX3CR1 V249I and T280M polymorphisms demonstrated that 13 out of 25 patients who died of infarction (52%) were homozygous for the V249 allele and 21 out of 25 (84%) were homozygous for the T280 allele." (PMID 24307998, 2013). "SCFAs generated by the gut microbiota may work by promoting the infiltration of CX3CR1+ macrophages in the peri‐infarct area, which is essential for healing cardiac damage after an infarction." (PMID 41479744, 2026).
leukemia (5 papers, 2013 to 2024). A malignant (clonal) hematologic disorder, involving hematopoietic stem cells and characterized by the presence of primitive or atypical myeloid or lymphoid cells in the bone marrow and the blood. "Furthermore, communication of the TCRγδ+ T-LGL leukemia cells with other immune cells was affected as reflected by the down-regulation of chemokine CX3CR1." (PMID 28407008, 2017). "Concordantly, the expression of surface proteins (CX3CR1, CXCR4, EMB, ITGB4, LSP, VCAM1) important for leukemia infiltration was downregulated in IGFBP2-null bone marrow AML cells." (PMID 24191913, 2013). "Finally, altered expressions of CD28, CCR7, CX3CR1, IFNG, LTB and PRF1 were all contributing to the inflammatory profile of the TCRγδ+ T-LGL leukemias." (PMID 28407008, 2017).
lung disease (5 papers, 2018 to 2025). "Here, we examined the role of the CX3CR1/CX3CL1 biological axis in the pathogenesis of SSc associated lung disease." (PMID 30457999, 2018). "This indicated that CX3CR1 was highly expressed in the pulmonary disease." (PMID 35222428, 2022). "Infecting mice with a virus with a mutated G that does not bind to CX3CR1 causes much lower levels of lung disease, which suggests that the G-CX3CR1 interaction is important to G-associated lung disease." (PMID 34372490, 2021). "Our study suggests that the inhibition of CX3CR1 expression could be a potential strategy for hypoxia-induced lung disease treatment, and also, to some extent, the activation of innate immunity such as macrophage polarization might be an effective therapeutic target towards PAH disease." (PMID 36246557, 2022).
neuropathic pain (5 papers, 2019 to 2022). Chronic pain caused by damage to nerve fibers. "Moreover, CX3C chemokine receptor 1 (CX3CR1)-deficient mice exhibited significantly reduced monocytes/macrophages in both inflammatory and neuropathic pain models." (PMID 33535595, 2021). "Thus, probably BET treatment is only effective on reducing pro-inflammatory mediators, such as TNF-α, CCL2, and CX3CR1, which are directly implicated in neuropathic pain." (PMID 31186006, 2019). "In summary, the present experiment demonstrated that the upregulation of IRF8 and CX3CR1 expressions as well as microglial activation in the spinal cord contributed to SNI-induced neuropathic pain." (PMID 32351637, 2020). "The fractalkine receptor, CX3CR1, a marker of peripheral monocytic cells and microglia, was increased in the ipsilateral DRG in a spared nerve injury-induced neuropathic pain model." (PMID 35204294, 2022).
periodontitis (5 papers, 2021 to 2025). An acute or chronic inflammatory process that affects the tissues that surround and support the teeth. "Higher CX3CL1 and CX3CR1 chemokine levels were found in subjects with periodontitis and RA compared with periodontal and systemically healthy subjects." (PMID 38415821, 2024). "This systematic review aimed to investigate the role of the CX3CL1/CX3CR1 axis in the pathogenesis of periodontitis and RA." (PMID 38415821, 2024). "This systematic review aimed to investigate the role of the C‐X3‐C motif ligand 1/chemokine receptor 1 C‐X3‐C motif (CX3CL1/CX3CR1) axis in the pathogenesis of periodontitis." (PMID 38415821, 2024). "Thus far, the CX3CL1/CX3CR1 axis's role in periodontitis is largely unsupported by the literature, with only six published studies." (PMID 38415821, 2024). "Therefore, this study seeks to assess the correlation between Fractalkine (CX3CL1) and the receptor for it (CX3CR1), as well as the different stages of periodontitis, to differentiate individuals with periodontitis from those who are periodontally healthy." (PMID 38590803, 2024). "Regarding pharmacological agents targeting the CX3CL1/CX3CR1 axis in the pathogenesis of periodontitis, it has been shown that the therapeutic CX3CR1 antagonist called “F1” was able to inhibit leukocyte recruitment in a murine model of thioglycolate‐induce periodontitis." (PMID 38415821, 2024). "Within the limitations of the present study and despite its promising clinical applications, it is too early to state that the CX3CL1/CX3CR1 axis can be used as a clinical tool to differentiate the condition of subjects with periodontitis and RA from periodontally and systemically healthy subjects." (PMID 38415821, 2024). "What is the role of the CX3CL1/CX3CR1 axis in subjects with periodontitis?" (PMID 38415821, 2024). "With the subquestion: Could the CX3CL1/CX3CR1 axis be used as a complementary tool to clinical parameters to distinguish between periodontitis and RA and/or systemically healthy subjects?" (PMID 38415821, 2024). "It would be premature to assert, however, that the CX3CL1/CX3CR1 axis can be leveraged as a clinical tool to distinguish between the status of patients with RA and periodontitis and that of periodontal and systemically healthy individuals in the lack of clinical data." (PMID 38415821, 2024). "Furthermore, our secondary objective was to determine whether the CX3CL1/CX3CR1 axis could be considered a clinical tool complementary to clinical parameters to distinguish between periodontitis and RA and/or systemically healthy subjects." (PMID 38415821, 2024). "In the future, we may generate myeloid specific NLRP3‐overexpression or knockout mice by crossing NLRP3‐Tg mice or NLRP3‐floxed mice with Lysm‐cre or CX3CR1‐cre mice and then establishing ligature‐induced periodontitis in the absence and presence of the NLRP3 inhibitor, MCC950." (PMID 33382502, 2021). "For the first time, this study compared healthy controls to patients with varying degrees of periodontitis and measured the amounts of protein (CX3CL1) and the receptor (CX3CR1) in their saliva." (PMID 38590803, 2024). "In comparison to the control group, patients with periodontitis had statistically increased salivary concentrations of CX3CL1 and CX3CR1 (P < 0.001)." (PMID 38590803, 2024). "The observational studies on human subjects diagnosed with periodontitis and RA and/or systemically healthy were selected to analyze CX3CL1 and CX3CR1 biomarkers." (PMID 38415821, 2024). "In relation to PD, it has been shown that levels of fractalkine/CX3CL1, CX3CR1 and IL-1β in FCG are increased in patients with periodontitis compared to periodontally healthy patients." (PMID 36770741, 2023). "Thus, increased expression and levels of the FKN‐CX3CL1/CX3CR1 axis have been observed in subjects with mainly Stage III/Grade B and C periodontitis compared with their healthy controls." (PMID 38415821, 2024).
pneumonia (5 papers, 2020 to 2026). An acute, acute and chronic, or chronic inflammation focally or diffusely affecting the lung parenchyma, caused by an infection in one or both of the lungs (by bacteria, viruses, fungi, or mycoplasma.). "In the immunocompromised state of patient 2, mutations in CX3CR1 may further weaken the immune system and consequently result in recurrent severe pneumonia." (PMID 36814216, 2023). "Specifically, FOXM1 can affect inflammation in pneumonia through NF-κB and the JAK/STAT signaling pathway and FOXM1 deficiency reduces the expressions of CCL11, CCL24 and chemokine receptors CCR2 and CX3CR1 to further affect inflammation." (PMID 36964598, 2023). "Our findings suggest phagocytosis‐induced signaling in CX3CR1+ tissue‐resident skeletal muscle macrophages is necessary for satellite cell proliferation during muscle recovery after influenza A virus‐induced pneumonia." (PMID 32720752, 2020).